KLRB1 (killer cell lectin like receptor B1)
Diseases named in the same sentence as KLRB1 in open-access papers (continued):
Sharing a sentence is not in itself a finding about the gene and the disease.
psoriasis (continued). "Conversely, negativity for either FABP5 or KLRB1 could indicate a protective factor against psoriasis." (PMID 38596682, 2024). "Notably, FABP5 and KLRB1 exhibited up-regulation and co-localization in psoriatic skin tissues and M5-induced HaCaT cells, serving as potential biomarkers influencing psoriasis development." (PMID 38596682, 2024). "Furthermore, through the integration of the LASSO, random forest, and SVM-RFE algorithms, we identified FABP5 and KLRB1 as robust markers in psoriasis." (PMID 38596682, 2024). "Thus, FABP5 and KLRB1 hold promise as significant biomarkers for psoriasis diagnosis." (PMID 38596682, 2024). "Our study analyzed the impact of DC-T cell crosstalk in psoriasis, elucidated the characterization of two biomarkers, FABP5 and KLRB1, in psoriasis, and highlighted the promise and value of tofacitinib in psoriasis therapy targeting DCs." (PMID 38596682, 2024). "Quantitative data from HALO revealed significantly higher mean values of positive cytoplasmic percentage for KLRB1 (33.24) and FABP5 (55.47) in the psoriasis group compared to the control group (9.932 and 14.30, respectively)." (PMID 38596682, 2024). "For example, in the Tcm compartment, excluding mitochondrial and ribosomal transcripts, only KLRB1, IL17R, and JUN were expressed at greater than 0.5 logFC in psoriasis compared to normal samples." (PMID 35958578, 2022). "Moreover, KLRB1 and FABP5 expression in HaCaT cells, an in vitro model of psoriasis induced by M5, was 1.93-fold and 4.158-fold higher than the control group, respectively." (PMID 38596682, 2024). "Still, single-cell analysis of skin tissues and peripheral blood mononuclear cells from Palmoplantar pustulosis, a specific psoriasis subtype, revealed heightened expression and co-expression of TH17 (KLRB1/CD161) and TH2 (GATA3) in a subset of memory CD4+ T cells." (PMID 38596682, 2024). "We identified unique expression profiles of KCs and DCs, further explored the importance of altered DC function in the development and progression of psoriasis, and identified two key genes, FABP5 and KLRB1, from the initially predicted 50 genes by a machine learning approach." (PMID 38596682, 2024).
hepatocellular carcinoma (14 papers, 2020 to 2026). A malignant tumor that arises from hepatocytes. "In our study, analysis of KLRB1 using the TCGA database demonstrated a significant association with T cell activation and immune response in hepatocellular carcinoma (HCC)." (PMID 38914941, 2024).
multiple sclerosis (13 papers, 2013 to 2025). A progressive autoimmune disorder affecting the central nervous system resulting in demyelination. "It is of note, that the human KLRB1 (CD161) gene has been identified as one genetic locus for the risk of developing multiple sclerosis." (PMID 26309225, 2015).
melanoma (11 papers, 2011 to 2025). A malignant, usually aggressive tumor composed of atypical, neoplastic melanocytes. "In a comprehensive analysis of the entire cancer genome, the gene KLRB1 encoding CD161 showed a good clinical prognosis in breast, colorectal, prostate, melanoma, and neuroblastoma carcinomas." (PMID 37351109, 2023). "To test this possibility, we identified four representative T/NK modules that tracked with survival differences in distinct tumor types (FOXP3.mod, PDCD1.mod, FLT3LG.mod and KLRB1.mod for bladder, head and neck, kidney and melanoma, respectively)." (PMID 26398410, 2015).
viral infections (11 papers, 2014 to 2025). "Notably, CD4+ T-cells in severe patients showed lower expression of the TNF superfamily ligands TNFSF10 (TRAIL) and TNFSF14 (LIGHT) and the surface protein SLAMF1 and KLRB1, all of which have roles in viral infections." (PMID 33178221, 2020).
glioblastoma (9 papers, 2021 to 2025). The most malignant astrocytic tumor (WHO grade IV). "Another study revealed that inactivation of the KLRB1 gene or antibody-mediated blockade of CD161 can enhance T cell-mediated anti-tumor functions in glioblastoma." (PMID 39202452, 2024). "In contrast, KLRB1 was highly expressed in glioblastoma multiforme (GBM), kidney renal clear cell carcinoma (KIRC), and kidney renal papillary cell carcinoma (KIRP)." (PMID 35028320, 2022).
Sepsis (9 papers, 2020 to 2026). Sepsis is defined as life-threatening organ dysfunction caused by a dysregulated host response to infection. "Interestingly, RETN and CD163 were positively correlated with the risk of sepsis-related death, whereas KLRB1 was negatively correlated with this risk." (PMID 41472734, 2025). "This analysis underscores the importance of multiple immunomodulatory proteins, particularly CD27, KLRB1, RETN, and CD163, in the risk of clinically overt sepsis, suggesting their potential as candidates for disease prognosis and treatment targets." (PMID 41472734, 2025). "Clinical studies further link higher KLRB1 expression to better outcomes, including longer overall survival in sepsis patients." (PMID 41472734, 2025). "Survival analysis revealed significant associations of KLRB1, RETN, and CD163 with sepsis prognosis." (PMID 41472734, 2025). "Although these findings derive from oncology, sepsis also features T-cell dysfunction, which suggests that KLRB1 could modulate the anti-pathogen immune response in sepsis through a comparable mechanism." (PMID 41472734, 2025). "This multidimensional regulatory network may initially present a pro-inflammatory state (dominated by CD27/RETN) in early sepsis, transitioning to immunosuppression (upregulation of KLRB1/CD163) in later stages." (PMID 41472734, 2025). "KLRB1 expression is up-regulated in early RA and MS and down-regulated in advanced RA and sepsis." (PMID 38774864, 2024). "Study showed that KLRB1 was identified as the downregulated crucial gene set in sepsis." (PMID 39654893, 2024). "The increased expression of KLRB1 on NK cells and T cells may be correlated with immune cell activation and inflammatory responses in sepsis." (PMID 38028617, 2023). "Lu J identified that KLRB1 was identified as the downregulated crucial gene set in sepsis." (PMID 36199375, 2022). "Notably, the expression levels of KLRB1, RETN, and CD163 are closely linked to patient prognosis and may serve as potential targets for future sepsis immunotherapy." (PMID 41472734, 2025). "In conclusion, our research revealed that CD27, KLRB1, RETN, and CD163 are highly specific and sensitive biomarkers for sepsis." (PMID 41472734, 2025). "We identified and validated CD27, KLRB1, RETN, and CD163 as key biomarkers of sepsis by integrating transcriptome and single-cell data using bioinformatics and machine learning." (PMID 41472734, 2025). "Study showed some hub genes (CD2, CD27, GZMA, KLRB1, and PRF1) have been screened out as sepsis biomarkers and all of them were down regulated genes in sepsis, which consistent with our findings." (PMID 39654893, 2024). "Our findings revealed significant decreases in CD4, CD3e, IL-7R, CD5, CD247, CD2, CD40LG, ITK, and KLRB1, and significant elevations in MMP9, LCN2, and RETN in sepsis-induced ARDS compared to controls." (PMID 37822934, 2023). "Drawing upon the insights gleaned from our murine sepsis-induced ARDS model and human subjects afflicted with sepsis-induced ARDS, we selected CD247, CD2, CD40LG, KLRB1, LCN2, and RETN as the foci of our subsequent investigation." (PMID 37822934, 2023). "By leveraging bioinformatics analysis and machine learning algorithms, we systematically identified five immune-related candidate hub genes (CLEC5A, KLRB1, LCN2, MCEMP1, and MMP9) and provided a nomogram for diagnosing ROP with sepsis." (PMID 38028617, 2023). "Based on this study’s findings and existing research theories, we propose that CD27, KLRB1, RETN, and CD163 may collaboratively regulate immune homeostasis in sepsis through their interactions." (PMID 41472734, 2025). "Further survival analysis revealed that while the expression levels of KLRB1, RETN, and CD163 significantly influenced sepsis prognosis, CD27 did not demonstrate statistical significance." (PMID 41472734, 2025).
tuberculosis (9 papers, 2013 to 2025). A chronic, recurrent infection caused by the bacterium Mycobacterium tuberculosis. "The signaling pathway most closely related to KLRB1 is tuberculosis, leishmaniasis, and inflammatory bowel disease pathway." (PMID 38608099, 2024).
Autoimmunity (8 papers, 2015 to 2025). The occurrence of an immune reaction against the organism's own cells or tissues. "However, we did observe a positive correlation of KLRB1 and C-peptide which may indicate a more active autoimmunity in patients with remaining C-peptide, as CD8+CD161+ cells exhibit a heightened cytotoxic memory." (PMID 40471289, 2025).
non-small cell lung carcinoma (8 papers, 2022 to 2026). A group of at least three distinct histological types of lung cancer, including non-small cell squamous cell carcinoma, adenocarcinoma, and large cell carcinoma. "Moreover, another study has reported that KLRB1 is also associated with a favorable outcome in non-small-cell lung cancer, which is consistent with our findings." (PMID 35028320, 2022). "KLRB1 (coding for CD161) gene expression shows a positive association with favorable outcome in non-small-cell lung cancer, independently of the size of T and B cell infiltrates, making CD161-expressing CD4+ T cells ideal candidates for anti-tumor recall responses." (PMID 35853971, 2022). "Other reports have shown that KLRB1 can be applied as a prognostic factor in esophageal squamous cell carcinoma and non-small-cell lung cancer." (PMID 35028320, 2022). "KLRB1 transcription is repressed in approximately 68% of people with non-small cell lung carcinoma, suggesting that KLRB1 could serve as a predictive tumor marker." (PMID 37351109, 2023).
liver cancer (7 papers, 2022 to 2025). An epithelial or non-epithelial malignant neoplasm that arises from the liver. "CD8+ T cells in recurrent liver cancer exhibit lower cytotoxicity compared to those in primary liver cancer and are characterized by a high expression of KLRB1." (PMID 38397459, 2024). "The results demonstrated that the expression of FCER1G, PFN1, ACTG1, PABPC1, CALM1, and RPS8 was significantly upregulated in the liver cancer cells, whereas KLRB1, LDB2, and FYN exhibited the opposite trend." (PMID 37397471, 2023). "In this study, through the analysis of the TCGA database and single-cell sequencing data from liver cancer tissues, we observed that KLRB1 is predominantly expressed on NK cells and T cells within liver cancer tissues, with a notably higher expression on NK cells compared to T cells." (PMID 38914941, 2024). "In addition, we also showed that patients with liver cancer expressing KLRB1 had a longer PFI." (PMID 35028320, 2022).
influenza (6 papers, 2014 to 2024). An acute viral infection of the respiratory tract, occurring in isolated cases, in epidemics, or in pandemics; it is caused by serologically different strains of viruses (influenzaviruses) designated A, B, and C, has a 3-day incubation period, and usually lasts for 3 to 10 days. "NK cell response related genes such as CD247, KIR2DL4, KIR3DL1, KIR3DL3 and KLRB1 were down-regulated only in moderate and severe patients while genes such as KIR2DL1, KIR2DS4 and KIR3DL2 were down-regulated in all three groups of influenza patients." (PMID 25365328, 2014). "In agreement, the NK cell receptor KLRB1 was shown as a negative predictor for vaccine response in the elderly, whereas NKG2C expression was reported as positively correlated with influenza vaccination in healthy individuals." (PMID 39331702, 2024).
leukemia (5 papers, 2011 to 2024). A malignant (clonal) hematologic disorder, involving hematopoietic stem cells and characterized by the presence of primitive or atypical myeloid or lymphoid cells in the bone marrow and the blood. "SELL, PTPRC, IL7R, CCR7, and KLRB1 were able to distinguish leukemia cells from normal cells well, with AUC values higher than 0.970." (PMID 38165493, 2024).
lung adenocarcinoma (5 papers, 2020 to 2025). A carcinoma that arises from the lung and is characterized by the presence of malignant glandular epithelial cells. "In this study, we aimed to evaluate the expression levels of KLRB1 in lung adenocarcinoma (LUAD) and analyze the relationship between KLRB1 expression levels, LUAD progression, and the tumor immune microenvironment." (PMID 38782996, 2024).
lung carcinoma (4 papers, 2021 to 2024). "In 25 cancers, including breast, bladder, liver, and lung cancer, the expression of KLRB1 was also positively correlated with the stromal score." (PMID 35028320, 2022). "However, the specific roles and mechanisms of KLRB1 in lung cancer remain unclear." (PMID 38782996, 2024).
neuroblastoma (4 papers, 2020 to 2026). Neuroblastoma (NB) is the most common solid, extracranial childhood tumor. "Six of these genes (CMBL, LY6E, KLRB1, CTSH, CD3D, and PTGDS) were utilized to construct a risk-scoring model that effectively stratified neuroblastoma patients into high- and low-risk groups with significantly distinct clinical outcomes (p < 0.001)." (PMID 41993132, 2026).
testicular germ cell tumor (4 papers, 2022 to 2024). A germ cell tumor arising from the testis. "Moreover, in LUAD, SKCM, STAD, THCA, and testicular germ cell tumors (TGCT), KLRB1 expression was also significantly correlated with tumor stage." (PMID 35028320, 2022).
uveitis (4 papers, 2018 to 2025). An inflammatory process affecting a part of or the entire uvea. "Clonally expanded CD8+ T cells in the eye in other forms of uveitis, however, did not express KLRB1, suggesting a pathogenic role specific to B27AAU." (PMID 39024572, 2024).
breast invasive carcinoma (3 papers, 2022 to 2025). "Breast invasive carcinoma (BRCA) patients with low KLRB1 levels were linked to advanced disease stages, poor prognosis, and a decreased survival probability compared to those with high KLRB1 expression." (PMID 40115278, 2025).
cholangiocarcinoma (3 papers, 2022). A carcinoma that arises from the intrahepatic biliary tree (intrahepatic cholangiocarcinoma) or from the junction, or adjacent to the junction, of the right and left hepatic ducts (hilar cholangiocarcinoma). "Cox regression analysis showed that KLRB1 was a low-risk factor associated with PFI in BLCA (p = 0.021), BRCA (p = 0.031), CESC (p = 0.025), cholangiocarcinoma (CHOL, p = 0.047), LIHC (p = 0.006), and UCEC (p = 0.033)." (PMID 35028320, 2022).
endometriosis (3 papers, 2019 to 2021). The growth of functional endometrial tissue in anatomic sites outside the uterine body. "We also identified putative inhibitory interactions between endometriosis immune cells and ectopic FBs rather than eutopic FBs, including KLRB1, TIGIT, and PDCD1, which were highly expressed by NK and T cells, and potentially bind to CLEC2D, NECTIN3, and FAM3C, which were expressed by FBs." (PMID 34233737, 2021).
malaria (3 papers, 2020 to 2024). Malaria is a serious and sometimes fatal disease caused by a parasite that commonly infects a certain type of mosquito which feeds on humans. "Moreover, protective vaccination was also found to reshape the malaria-induced response of the KLRB1:CLEC2 system operating as an MHC class I-independent surveillance system in the liver." (PMID 33202767, 2020).
oropharyngeal cancer (3 papers, 2023 to 2025). Carcinoma, predominantly squamous cell, arising from the epithelial cells of the oropharynx. "For example, in the context of oropharyngeal cancer, evidence shows that the KLRB1 gene (encoding CD161) enhances the anti-tumor effect when expressed in CD4+ follicular helper cells, but functions as an immune suppressor when expressed in CD8+ T cells." (PMID 40148916, 2025).
sarcoma (3 papers, 2022). A usually aggressive malignant neoplasm of the soft tissue or bone. "Interestingly, the expression levels of KLRB1 and TOP1 were significantly associated with the survival of sarcoma patients (p < 0.05), indicating that they could be potential prognostic markers." (PMID 36118864, 2022).
acute myeloid leukemia (2 papers, 2022 to 2025). Acute myeloid leukemia (AML) is a group of neoplasms arising from precursor cells committed to the myeloid cell-line differentiation. "The results showed that in 17 tumors such as BRCA, LIHC, LUAD, and STAD, the expression of KLRB1 was positively correlated with TMB, but the opposite was true in acute myeloid leukemia (LAML) and brain lower-grade glioma (LGG)." (PMID 35028320, 2022).
atherosclerosis (2 papers, 2015 to 2023). A disease characterized by the build-up of fatty material and calcium deposition in the arterial wall resulting in partial or complete occlusion of the arterial lumen. "Furthermore, anti-inflammatory/inflammation-regulatory genes (like IL7R, ANXA1, and KLRB1) and pathways (like regulation of IL-2 production) were decreased in CD4+ T cells (T_1, T_2, and T_3) from atherosclerosis compared with those from NC." (PMID 37706320, 2023).
brain glioma (2 papers, 2021 to 2022). A malignant glioma that involves the brain. "Unlike these cancers, patients with low-grade brain gliomas having high KLRB1 expression exhibit a worse prognosis." (PMID 35028320, 2022).
depression (2 papers, 2022 to 2025). "The association between KLRB1 and inflammatory markers in patients with MDD further supports its role in bridging the gap between immunity and depression." (PMID 40689242, 2025).
esophageal squamous cell carcinoma (2 papers, 2020 to 2022). Esophageal squamous cell carcinoma (ESCC) is a type of esophageal carcinoma (EC) that can affect any part of the esophagus, but is usually located in the upper or middle third. "Transcription of KLRB1 was suppressed in 68% of NSCLC (non-small cell lung cancer) and 57% of esophageal squamous-cell carcinoma patients indicating that CD161 can be a predictive marker in these indications." (PMID 33597948, 2020).
hepatic diseases (2 papers, 2014 to 2024). "In recent studies, KLRB1 has been found to be one of the potential markers of liver diseases such as cirrhosis." (PMID 39596644, 2024). "Therefore, it will be important to understand what process KLRB1 involved in the liver for the prevention of liver diseases." (PMID 39596644, 2024). "Most recently, a few studies have reported the correlation of KLRB1 with hepatic diseases." (PMID 39596644, 2024).
kidney cancer (2 papers, 2022). Primary or metastatic malignant neoplasm involving the kidney. "KLRB1 was downregulated in 13 cancers while upregulated in kidney cancer." (PMID 35028320, 2022). "Interestingly, the expression of KLRB1 in kidney cancer tissues (KIRC and KIRP) showed the opposite results." (PMID 35028320, 2022). "KLRB1 was attenuated in 13 cancers and promoted in kidney cancer." (PMID 35992798, 2022).
breast tumors (1 paper, 2023). "Results of TISCH proved that when compared to stromal cells in BC, KLRB1 expression in immune cells was relatively higher, implying the vital role of KLRB1 in the TME of breast tumors." (PMID 37520246, 2023). "IHC staining showed that KLRB1 staining was weaker in breast tumor tissues than in paratumors." (PMID 37520246, 2023).
gout (1 paper, 2023). A condition characterized by painful swelling of the joints, which is caused by deposition of urate crystals. "In contrast, the DEGs of KLRB1+CD4+ TCs from the gout flare patient group only exhibited enrichment for the IL-17 signaling pathway." (PMID 38063198, 2023). "The IL-16 ligand and its CD4 receptor were also highly active during gout flares in CMs, myeloid cells, Tregs, and KLRB1+CD4+ TCs." (PMID 38063198, 2023). "KEGG analysis indicated that the DEGs of KLRB1+CD4+ TCs from gout remission were enriched for the FoxO signaling pathway." (PMID 38063198, 2023).